FGFR2 (fibroblast growth factor receptor 2)
Diseases named in the same sentence as FGFR2 in open-access papers (continued):
Sharing a sentence is not in itself a finding about the gene and the disease.
gastric cancer (continued). "Receptor tyrosine kinase (RTK)-related genes, including HER2, EGFR, MET, FGFR2 and KRAS, are target molecules that are clinically beneficial in gastric cancer (GC)." (PMID 27014419, 2016). "Amplification of seven oncogenes: HER2, EGFR, FGFR1, FGFR2, MET, KRAS and IGF1R has been identified in gastric cancer." (PMID 27437872, 2016). "Approximately 7-17% of advanced gastric cancers have HER2 overexpression or amplification, 2-7% have FGFR2 amplification and 2-8% have MET amplification." (PMID 27437872, 2016). "Even in our initial screening, FGFR2 expression, similar to that of NKX2.1 correlates well with that of EGFR expression in primary gastric cancer." (PMID 25154973, 2015). "In order to determine the optimal therapeutic target for future studies, the question that needs to be resolved is which of EGFR, FGFR2, and NKX2.1 is the most upstream and the critical alteration in primary gastric cancer." (PMID 25154973, 2015). "We previously reported that FGFR2 activated AKT and ERK signaling pathways in FGFR2 amplified gastric cancer cell lines." (PMID 24968263, 2014). "The K-sam gene, which is known to exacerbate scirrhous gastric cancer, has also been revealed to be homologous to other genes, including FGFR2, KGFR and Bek." (PMID 23545898, 2013). "Biomarkers such as microsatellite instability (MSI), HER2, and programmed death-ligand 1 (PD-L1) have already made an impact in the treatment of gastric cancer, and new biomarkers have recently been identified, such as claudin 18.2 (CLDN18.2) and fibroblast growth receptor 2 (FGFR2)." (PMID 41303727, 2025). "Furthermore, a comprehensive multi-omic analysis of malignant gastric cancers revealed genomic amplifications of established cancer driver genes such as EGFR, ERBB2, MET, FGFR2, and CD44 in gastric cancer with peritoneal metastasis." (PMID 41009730, 2025). "Utilizing CCA, gastric cancer cell lines, and patient‐derived xenograft models (PDX), we demonstrate that CA3 is effective in inducing cell death and delaying tumor growth in both FGFR2 fusion and wild‐type models." (PMID 39300603, 2024). "In the preliminary investigation using RNAseq data of gastric cancer patients’ tissue, we found that the combined evaluation of RTKs, such as MET and FGFR2 amplification, could identify the specificity of gastric tumor cells when compared to normal tissue." (PMID 38137393, 2023). "The positive reciprocal regulation of FGFR2 and CD44 was found to be important in gastric cancers." (PMID 37443779, 2023). "Another study aiming to explore the ability of miR-494 and FGFR2 to regulate the cancer-initiating cell phenotype and the therapeutic efficacy of lapatinib in HER2-positive gastric cancer found that increased miR-494 expression was able to reduce lapatinib resistance in these cells." (PMID 38201452, 2023). "Similarly, FGFR2 activates the PI3K/AKT/mTOR axis and its downstream TSP1, which regulates migration and invasion of gastric cancer cells." (PMID 37750089, 2023). "FGF18, a ligand for FGFR2, interacts with FGFR2, enhances F‐actin, and then promotes nuclear aggregation of YAP1; FGFR2 also activates the MAPK pathway and its downstream molecule, c‐Jun, which upregulates YAP1 transcription to promote the progression of gastric cancer." (PMID 37750089, 2023). "While the majority of Her2/neu-amplified gastric carcinomas show an intestinal growth pattern (according to the Lauren classification), this is not true for FGFR2-amplified tumors." (PMID 36416959, 2023). "In tumor with FGFR2 amplification, trials on the efficacy of inhibitors of FGFR2, such as Dovitinib (NCT01719549) or AZD4547 (NCT01457846), are ongoing in the metastatic setting and, therefore, are far away to be tested in resectable gastric cancer." (PMID 36230592, 2022).
gastric cancer (continued). "Notably, insulin receptor levels are visualised easily in three of the four gastric cancer cell lines and in the metastatic cells that represent the majority of gastric cancers that are triple-negative for ERBB2, FGFR2 or MET overexpression." (PMID 34554347, 2022). "In the Venn diagram intersection of recognized targets about identified chemical compounds and gastric cancer, a total of 23 gastric cancer genes are acquired among which the top six genes ABCG2, MUTHY, TRET, POLE, BRAF and G, and FGFR2 were used to produce Venn diagram." (PMID 36500601, 2022). "Although it has been proposed that FGFR2 is coexpressed and colocalized with CD44 in gastric cancer cells, it is still unclear whether the association between these two proteins exists in ECs." (PMID 36463112, 2022). "By contrast, AZD4547 did not obviously improve PFS versus paclitaxel in gastric cancer patients harboring FGFR2 amplification." (PMID 33568192, 2021). "Several FGFR2 tyrosine kinase inhibitors (TKIs), including AZD4547 (NCT01457846, SHINE trial), dovitinib (NCT01719549), E7090 (NCT02275910), and TAS-120 (NCT02052778), have been evaluated for patients of gastric cancer with FGFR2 amplification." (PMID 33633310, 2021). "Overall, the most frequently mutated drug target genes were BRAF for thyroid cancer, FGFR2 for endometrial cancer, EGFR for brain tumors, MGMT for colorectal cancer, FGFR2 and FGFR3 for bladder cancer, NTRK3 for non-small cell lung cancer and NTRK2, FGFR2, EGFR for stomach cancer." (PMID 32111026, 2020). "Finally, the role of mutated NTRK3 as target gene for treatment of non-small cell lung cancer is exploited by clinical trials, whereas targeting FGFR2 and EGFR in stomach cancer is considered promising for improving current strategies." (PMID 32111026, 2020). "First, several truncated versions of FGFR2 lacking the C-terminal tail, including S780, have been identified in thyroid, skin, endometrial, and gastric cancers." (PMID 31146385, 2019). "For example, overexpression of FGFR2 promotes the proliferation and survival of gastric cancer cells through activating the downstream MAPK/ERK and PI3K/AKT signaling pathways 10, and FGFR2 enhances the phosphorylation activity of RSK2 and regulates the migration of human mammary epithelial cells." (PMID 31523191, 2019). "In a phase I study of LY2874455 in patients with advanced-stage solid cancers, there were two partial responses (4%, 2/51) seen in patients with FGFR2 non-amplified gastric cancer." (PMID 35582593, 2019). "We previously reported that high levels of tyrosine kinase receptor (RTK) gene amplification of EGFR, HER2, FGFR2, or MET had protein overexpression and rarely showed other coexisting gene alterations using the next-generation sequencing (NGS) method for gastric cancer." (PMID 28852882, 2018). "We analyzed the expression level of gastric cancer-related genes EGFR, FGFR2, KLF4, DNMT1 and AGO4 identified through bioinformatics screening by relative quantification method and observed differential expression of EGFR, FGFR2, KLF4, DNMT1 and AGO4 in tumors." (PMID 29719612, 2018). "Clinical studies selecting FGFR2-positive gastric cancer patients based on FGFR2 gene amplification with different methods are currently ongoing; however, no FGFR2-targeted agent along with a biomarker assay has been approved yet." (PMID 28852882, 2018). "FGFR2 mRNA expression rather than FGFR2 gene amplification has been discussed as a biomarker to select patients for FGFR2-targeted therapies in gastric cancer." (PMID 28852882, 2018). "In conclusion, FGFR2 amplification is not an independent prognostic predictor in patients with metastatic or locally advanced gastric cancer treated with palliative FP." (PMID 27802183, 2017).
gastric cancer (continued). "Amongst the gastric cancer cell lines analyzed, NCI-N87 expressed high levels of HER2, KATO III and SNU-16 expressed high levels of FGFR2 and SNU-5 overexpressed c-Met consistent with reported amplification of the genes that encode these tyrosine kinase receptors." (PMID 27437872, 2016). "MET, ATM, FGFR2, and HER2 were profiled on gastric cancer biopsy samples." (PMID 26587992, 2015). "Examples of this heterogeneity can be seen with Met staining in lung cancer and FGFR2 staining in gastric cancer (B Lutterbach, C. Ware, data not shown)." (PMID 24968263, 2014). "In gastric cancer FGFR2 amplification can occur in a metastatic tumor but not in the associated primary tumor, also consistent with a role in metastatic and late stage cancer." (PMID 24968263, 2014). "In six cases, the copy number of FGFR2 was larger than 10 copies and numerous signals were observed by the FISH analysis, indicating that these gastric cancer cells harboured high levels of amplification, similar to the results obtained using gastric cancer cell lines." (PMID 22240789, 2012). "The K-sam gene was first identified and characterised as an amplified gene in the human gastric cancer cell line KATO-III, and its product was later found to be identical to the bacteria-expressed kinase, or keratinocyte growth factor receptor, and FGF receptor 2 (FGFR2)." (PMID 22240789, 2012). "This study evidences previously observed perturbations of the KRAS, ERBB2, EGFR, MET, PIK3CA, FGFR2 and AURKA genes in gastric cancer and suggests some of the targeted therapies approved or in clinical development would be of benefit to 11 of the 50 patients studied." (PMID 21781349, 2011). "Likewise, the FGFR2-specific degrader N5, generated by coupling erdafitinib to a CRBN ligand, achieves exceptional FGFR2 degradation (DC50 = 0.03 nmol/L) with minimal off-target activity, and exerts strong antiproliferative effects in FGFR2-amplified gastric cancer cells and xenografts." (PMID 41584352, 2026). "For example, in the gastric cancer cell line, SNU16, at least three distinct species of ecDNA exist independently from chromosomes; those that localize the MYC (chr 8) oncogene, those that localize the FGFR2 (chr 10) oncogene, and those that co-localize MYC (chr 8), FGFR2 and CD44 (chr 11) genes." (PMID 39091515, 2024). "Therefore, the combination therapy of MET and FGFR2 inhibitors may be a promising strategy to treat the inherent resistance of MET inhibitors in gastric cancer cases containing MET and FGFR2 amplification." (PMID 35664756, 2022). "However, we found that FGFR2 amplification was unlikely to affect PD-L1 expression levels in gastric cancer, with a broad range of PD-L1 expression levels detected regardless of FGFR2 copy number." (PMID 35342406, 2022). "The overall survival and disease-specific survival of the gastric cancer patients with FGFR2IIIb and/or FGFR2IIIc expression (n = 28) was significantly poorer than that of the patients with FGFR2-negative expression (n = 534) (p = 0.008 and 0.002, respectively)." (PMID 33633310, 2021). "FGFR2 gene amplification was also associated with RFS but not with OS in an invariant analysis, and does not appear to be an independent prognostic predictor of RFS in gastric cancer." (PMID 28852882, 2018). "As the accompanying FGFR2 amplification did not affect the chemotherapy response in advanced gastric cancer in present and previous studies, it could be hypothesized that the FGFR2 inhibitor would be more effective when combined with cytotoxic agents." (PMID 27802183, 2017). "Another possible hypothesis states that FGFR2 inhibitor monotherapy itself was not effective for advanced gastric cancer due to the presence of other escape mechanisms." (PMID 27802183, 2017). "Notably, the prognostic impact of FGFR2 amplification observed in the present study did not markedly differ from that in previous studies on advanced gastric cancer patients who received palliative chemotherapy." (PMID 27802183, 2017).
gastric cancer (continued). "To date, several studies have reported on the protein expression of FGFR2 and clinicopathological analyses using immunohistochemistry, with 20 of 49 (41%) and 42 of 134 (31%) gastric cancers expressing FGFR2 protein when evaluated using positive or negative staining." (PMID 22240789, 2012). "Chromosome 10 harbors the oncogene FGFR2 (10q26) and tumour suppressor genes PTEN/MMAC1 (10q23) and DMBT1 (10q25-q26), both involved in carcinogenesis, which could explain the observation of both gains and losses of chromosomes 10 in gastric carcinomas." (PMID 17908304, 2007). "Although it can be reasonably assumed that FGFR2 amplification is a negative prognostic indicator in patients with resectable gastric cancer, these results cannot be applied to metastatic or locally advanced unresectable gastric cancer, as noted in the present and recently published studies." (PMID 27802183, 2017). "Met or PLEKHA5 silencing also blocked the growth of MKN45 cells but did not affect that of other gastric cancer cell lines, including KATO-III that has FGFR2 gene amplification, and normal mesothelial cell line without Met gene amplification." (PMID 33677467, 2021). "Overall, although FGFR2 has attracted tremendous attention as a potential therapeutic candidate in gastric cancer, the function of SPRY, the key molecule inhibiting FGFR2 signaling, has not been well elucidated." (PMID 28002800, 2017). "In addition, patients with FGFR2 protein expression determined by IHC, exhibited a better response (85.7%) after combination treatment with pazopanib, capecitabine, and oxaliplatin in a phase II trial, in comparison with patients without FGFR2 protein expression (59.5%) in advanced gastric cancer." (PMID 27802183, 2017). "Though FGFR2 and CD44 signals are frequently deregulated and are important in GC growth and maintenance in vitro and in vivo, the cooperative roles of FGFR2 and CD44 in the context of gastric cancer stemness factors have not been studied." (PMID 27107424, 2016). "The type I IGF receptor was expressed also in gastric cancer cells isolated directly from patients that do not express HER2, FGFR2 or c-Met." (PMID 27437872, 2016). "We examined the growth inhibitory effect of PD173074 (0.004–80 μM) on four FGFR2-amplified (HSC-43, TU-KATPIII, SNU-16 and HSC-39) and four non-amplified (44As3, 58As1, IM95 and OCUM1) gastric cancer cell lines." (PMID 22240789, 2012). "However, all cases of GC exhibited positive PD-L1 expression regardless of whether FGFR2 genetic alterations were present (CPS, 1–10), suggesting that anti-PD-L1 therapy may be beneficial in the treatment of gastric cancer." (PMID 35342406, 2022). "Indeed, in a gastric cancer cell line, where FGFR2 ecDNA and MYC ecDNA are in a hub, interference of FGFR2 enhancers decreased MYC expression, but interference of MYC enhancers did not affect FGFR2 expression." (PMID 37415185, 2023).
craniosynostosis (114 papers, 2006 to 2025). Craniosynostosis is defined as the premature fusion of one or more cranial sutures leading to secondary distortion of skull shape resulting in skull deformities with a variable presentation. "Apert syndrome is a severe autosomal dominant disorder caused by recurrent FGFR2 mutations, characterized by the prenatal triad of craniosynostosis, midface hypoplasia, and symmetric syndactyly." (PMID 41268110, 2025). "Pathogenic variants in FGFR2 are primarily associated with skeletal dysplasias characterized by craniosynostosis as a key feature, while bone fragility and osteoporosis are not commonly recognized manifestations." (PMID 40362441, 2025). "In mouse models that harbor gain-of-function Fgfr2 variants associated with human craniosynostosis syndromes, mechanisms of premature fusion of the coronal suture include altered proliferation and induction of ectopic osteoblast differentiation." (PMID 39775862, 2025). "Pathogenic variants in FGFR2 are associated with the development of syndromic craniosynostosis, such as Crouzon, Apert and Pfeifer syndromes." (PMID 40843495, 2025). "Identifying FGFR2 pathogenic variants in craniosynostosis highlights their vital role as signal transducer molecules during the normal development of cranial sutures." (PMID 40261605, 2025). "In conclusion, this paper describes the generation of three patient-derived FGFR2-linked craniosynostosis hiPSCs, each with a different pathogenic mutation in the gene." (PMID 40843495, 2025). "In particular, this FGFR2 variant has been identified in several unrelated individuals with Apert syndrome (approximately 71%) and other FGFR2-associated craniosynostosis syndromes." (PMID 40843798, 2025). "Each of these gain-of-function variants reveal a distinct effect on the phosphorylation of FGFR2 in craniosynostosis and between individual patients." (PMID 40843495, 2025). "These patient hiPSC lines provide molecular and cellular options to investigate FGFR2-linked craniosynostosis in the patient-specific genomic context and develop therapeutic modalities." (PMID 40843495, 2025). "AS makes up 4.5% of cases of craniosynostosis and is caused by pathogenic variants of the FGFR2 gene." (PMID 40261605, 2025). "The access and availability of these patient-specific in vitro disease models are important as they recapitulate FGFR2-linked craniosynostosis, with the cellular context and genetic makeup of the patient." (PMID 40843495, 2025). "Pathogenetic variants in FGFR2 have been associated with various phenotypes, with craniosynostosis as the main clinical finding in most of them." (PMID 40362441, 2025). "Among these, FGFR2 mutations are associated with the onset of various types of craniosynostosis, with Crouzon syndrome being the most common, and bilateral coronal craniosynostosis serving as one of the main features of syndromic craniosynostosis." (PMID 41390905, 2025). "Crouzon syndrome, which is a hereditary craniosynostosis, can be the result of inheritance from either parent, as well as de novo mutations in the FGFR2 gene." (PMID 40995454, 2025). "The genetic syndromes that associate craniosynostosis determined by FGFR2 gene mutations are autosomal dominant and show a variable degree of overlap of some clinical signs." (PMID 39061616, 2024). "Craniosynostosis is commonly linked to mutations in FGFRs, with FGFR2 (OMIM 176943) being the most frequently implicated in craniosynostosis syndromes." (PMID 38561822, 2024). "FGFR2 is important in skeletal growth and bone density and mutations in FGFR2 are linked to a variety of craniosynostosis syndromes in humans." (PMID 38469138, 2024). "Reports have shown that the majority of craniosynostosis syndromes were related to FGFR2 gain-of-function mutations." (PMID 37325554, 2023). "Genes most commonly mutated in familial craniosynostosis include, besides FGFR2 and FGFR3, the twist family bHLH transcription factor 1 (TWIST1) and ephrin-B1 (EFNB1)." (PMID 37441579, 2023).